SCAMP1 (secretory carrier membrane protein 1)
Diseases named in the same sentence as SCAMP1 in open-access papers (continued):
Sharing a sentence is not in itself a finding about the gene and the disease.
osteosarcoma (1 paper, 2022). A usually aggressive malignant bone-forming mesenchymal neoplasm, predominantly affecting adolescents and young adults. "Moreover, we performed several molecular biological approaches to define the underlying mechanism by which lncRNA SCAMP1 regulated cell viability and invasion in osteosarcoma." (PMID 35992869, 2022). "In this study, we utilized multiple cellular biological approaches to determine the function of lncRNA SCAMP1 in osteosarcoma cells." (PMID 35992869, 2022). "Taken together, lncRNA SCAMP1 overexpression promotes cell viability via miR-26a-5p in osteosarcoma cells." (PMID 35992869, 2022). "In our study, we reported that lncRNA SCAMP1 modulated the expression of ZEB2 via sponging miR-26a-5p in osteosarcoma, which led to promotion of cell viability and colony formation." (PMID 35992869, 2022). "In summary, lncRNA SCAMP1 modulated the expression of ZEB2 via sponging miR-26a-5p in osteosarcoma, which resulted in promotion of viability and colony formation of osteosarcoma cells." (PMID 35992869, 2022). "For instance, the current study used cell culture system to define the role of lncRNA SCAMP1 in osteosarcoma." (PMID 35992869, 2022). "In the current study, we observed that lncRNA SCAMP1 promoted cell invasion and migration in osteosarcoma cells." (PMID 35992869, 2022). "We also reported that lncRNA SCAMP1 promoted cell invasiveness and migrative capacity in osteosarcoma cells via regulating miR-26a-5p/ZEB2 axis." (PMID 35992869, 2022). "We dissected that lncRNA SCAMP1 promoted progression of osteosarcoma via modulation of miR-26a-5p/ZEB2 axis." (PMID 35992869, 2022). "On the contrary, both osteosarcoma cell lines with SCAMP1 cDNA transfection had a faster rate to close the wound area." (PMID 35992869, 2022). "To check the function of lncRNA SCAMP1 in osteosarcoma cells, we transfected the SCAMP1 cDNA into MG63 and U2OS cells using Lipofectamine 2000." (PMID 35992869, 2022). "Moreover, we performed several molecular biological approaches to define the mechanism by which lncRNA SCAMP1 regulated cell viability and invasion in osteosarcoma." (PMID 35992869, 2022). "Since ZEB2 is the critical driver in EMT progression, it is needed to address whether lncRNA SCAMP1 can regulate the EMT in osteosarcoma via targeting ZEB2." (PMID 35992869, 2022). "Therefore, we used the wound healing assay in our study to check the role of lncRNA SCAMP1 in regulation of migration in osteosarcoma cells." (PMID 35992869, 2022). "Therefore, it is necessary to describe that in vivo experiments and clinical sample study are required to determine the role of lncRNA SCAMP1 in osteosarcoma." (PMID 35992869, 2022). "We used Transwell invasion assay to test the function of lncRNA SCAMP1 in osteosarcoma cells." (PMID 35992869, 2022). "Moreover, lncRNA SCAMP1 performed their functions on cell motility via targeting miR-26a-5p/ZEB2 axis in osteosarcoma." (PMID 35992869, 2022). "It is required to investigate whether lncRNA SCAMP1 targets ZEB1 in osteosarcoma cells." (PMID 35992869, 2022). "Hence, lncRNA SCAMP1 could govern the invasive and migrative abilities in osteosarcoma cells." (PMID 35992869, 2022). "Therefore, we aimed to explore the lncRNAs that could bind to lncRNA SCAMP1 in osteosarcoma cells." (PMID 35992869, 2022). "In a word, lncRNA SCAMP1 regulated cell invasiveness and migrative ability through targeting miR-26a and ZEB2 pathways in osteosarcoma." (PMID 35992869, 2022). "Moreover, we tested whether lncRNA SCAMP1 regulated the expression of ZEB2 in osteosarcoma cells." (PMID 35992869, 2022). "Therefore, lncRNA SCAMP1 could govern the viability of osteosarcoma cells." (PMID 35992869, 2022). "The mechanisms of lncRNA SCAMP1-mediated tumorigenesis have not been determined in human osteosarcoma." (PMID 35992869, 2022). "In conclusion, targeting lncRNA SCAMP1 and its downstream targets, miR-26a-5p and ZEB2, might be a useful approach for osteosarcoma therapy." (PMID 35992869, 2022).
osteosarcoma (continued). "This study did not use the mouse model and clinical tissues from osteosarcoma patients to dissect the function of SCAMP1." (PMID 35992869, 2022). "However, the mechanisms of lncRNA SCAMP1-involved tumorigenesis have not been reported in human osteosarcoma." (PMID 35992869, 2022).
stomach adenocarcinoma (1 paper, 2024). "We found that SCAMP1 mRNA expression was markedly increased in most of the tested cancer types, including stomach adenocarcinoma (STAD) tissues, compared with normal tissues (P < 0.001)." (PMID 39308691, 2024).
triple-negative breast carcinoma (1 paper, 2021). An invasive breast carcinoma which is negative for expression of estrogen receptor (ER), progesterone receptor (PR), and human epidermal growth factor receptor 2 (HER2). "The cooperative activity of MTSS1 and SCAMP1 prevents triple-negative breast cancer cell invasion whilst their silencing enhances the aggressiveness of these cancer cells." (PMID 33493138, 2021). "SCAMP1 dampens down the invasive ability of MTSS1 in triple-negative breast cancer cells through the trafficking mediated upregulation of RAC1-GTP, thus enhancing cell adhesion." (PMID 33493138, 2021).
cancer (8 papers, 2018 to 2025). A tumor composed of atypical neoplastic, often pleomorphic cells that invade other tissues. "Secretory carrier membrane protein 1 (SCAMP1) is a lncRNA that promotes cancer progression through cell viability and invasion." (PMID 38339387, 2024). "Secretory Carrier Membrane Protein 1 (SCAMP1) has been reported to be involved in the progression of various cancers." (PMID 34512152, 2021). "Taken together, these observations highlight the cooperation of MTSS1 and Scamp1 in preventing HER2+/ER−/PR− cancer progression and provide further insights on early events associated with the pathogenesis of cancer invasion." (PMID 29497041, 2018). "We first examined SCAMP1 expression across various cancer types from the TCGA." (PMID 39308691, 2024). "Moreover, univariate analysis indicated that age, metastasis, SCAMP1 expression and SCAMP5 expression were significantly associated with the risk of cancer-related death." (PMID 33493138, 2021). "Importantly, co-expression of MTSS1 and SCAMP1 resulted in a more efficient inhibition of cell invasion and increased cell–cell adhesion in our cancer models when compared to the expression of Mtss1 or Scamp1 alone." (PMID 29497041, 2018). "However, fairly little is known about the functions of SCAMPs, including SCAMP1, in cancer." (PMID 39308691, 2024). "In addition to its membrane trafficking and cancer-related function, we demonstrated the previously unknown antiviral function of SCAMP1 against HBV infection." (PMID 35216324, 2022). "For the six remaining NETs-related lncRNAs (AC020765.2, SCAMP1.AS1, AL035587.1, AP000695.2, AP004608.1, and MMP2.AS1), there have been no studies exploring their potential roles in the development of cancer at present." (PMID 34257164, 2021). "Therefore, SCAMP1 and CHM may play a role in regulating the growth, survival and invasion of cancer cells." (PMID 40458711, 2025).
tumor (6 papers, 2018 to 2024). "NCI-N87 cells with SCAMP1 knockdown grew more slowly than control cells, and SCAMP1 deficiency limited the weights of the harvested tumor masses derived from NCI-N87 cells." (PMID 39308691, 2024). "HER2+/ER−/PR− phenotype tumours showed increased loss of SCAMP1 protein compared to other HER2+ classes (p = 0.034)." (PMID 29497041, 2018). "Moreover, increased SCAMP1 protein levels were associated with increased tumor size (P = 0.028) and positive lymph node metastasis (P = 0.015)." (PMID 39308691, 2024). "In summary, we demonstrated that SCAMP1 knockdown suppresses proliferation by deactivating multiple tumor-promoting signaling pathways in GC cells." (PMID 39308691, 2024). "In this study, we demonstrated that SCAMP1 expression was aberrantly increased in GC tissues and was positively correlated with tumor size and lymph node metastasis." (PMID 39308691, 2024). "Meanwhile, overexpression of miR‐499a‐5p reversed the tumour inhibitory effects induced by SCAMP1 knockdown." (PMID 31207033, 2019). "Strikingly, SCAMP1 knockdown combined with miR‐499a‐5p overexpression predominantly reduced xenograft tumour growth and elongated the nude mice survival time." (PMID 31207033, 2019). "Unfortunately, the evidence to support that tumor-derived SCAMP1 systematically influences malignant progression is sparse; however, the emerging functions of SCAMP1 in synaptic transmission will prompt further investigations into its possible roles in broader areas." (PMID 39308691, 2024). "The downregulation of SCAMP1 suppresses the migration and invasion of tumor cells." (PMID 33493138, 2021). "There is compelling evidence supporting the correlation between aberrant Cx43 expression and tumor growth or metastasis.Secretory carrier membrane protein 1 (SCAMP1) has been reported as a key functional protein in various tumors; it also functions as a long noncoding RNA (lncRNA) in human tumors." (PMID 34221012, 2021). "On the contrast, SCAMP1 also showed tumor-promoting activity in other solid cancer." (PMID 34426610, 2021).
infection (1 paper, 2009). The state of being infected such as from the introduction of a foreign agent such as serum, vaccine, antigenic substance or organism. "At 29 dpi, in particular, a highly significant two-fold increase in expression of the SCAMP1 gene was detected in PBMC from the N'Dama group (P = 0.0031) relative to pre-infection levels." (PMID 19409086, 2009). "STX7 and SCAMP1 transcript levels, which generally increased over the time course, were only significantly increased in expression in N'Dama relative to pre-infection and at 25 dpi N'Dama had 1.4-fold higher levels of STX7 mRNA relative to Boran." (PMID 19409086, 2009).
SCAMP1 also shares sentences with these, for which no sentence is quoted: cervical cancer (2 papers); acute lymphoblastic leukemia (1); acute myeloid leukemia (1); B-cell acute lymphoblastic leukemia (1); COVID-19 (1); Delusion (1); gastric cancer (1); leukemia (1); non‐small cell lung cancer (1); T-cell leukemia (1).